FOXA2 (forkhead box A2)
Diseases named in the same sentence as FOXA2 in open-access papers (continued):
Sharing a sentence is not in itself a finding about the gene and the disease.
Obesity (14 papers, 2012 to 2025). Accumulation of substantial excess body fat. "Foxa2 deficiency in mouse pancreatic cells under HFD conditions leads to increased obesity and reduced glucose uptake and glycolysis." (PMID 40292466, 2025). "FOXA2 (Entrez Gene: 3170) is reported to negatively regulate basal transcription and expression of the human fat mass and obesity-associated gene, which is involved in regulating dietary intake and energy expenditure." (PMID 24392026, 2013). "An example is the genomic locus of Fto (fat mass and obesity associated gene), where Foxa1 and Foxa2 bind four distinct intronic regions." (PMID 22737085, 2012). "Furthermore, cholestasis in FOXA2-deficient mice in the liver induces inflammatory signaling that activates the mTOR signaling pathway to increase hepatic lipogenesis and obesity in mice." (PMID 38605023, 2024). "For example, ginger PELNs contain abundant PA, which induces Foxa2 expression in intestinal epithelial cells, thereby preventing high-fat diet-induced obesity and insulin resistance." (PMID 39239509, 2024). "Apart from common DIS regulated genes the transcription factors FOXO1 and FOXA2 and the insulin induced gene 2 are specific targets of miR-335-5p; note polymorphisms of INSIG2 are associated with severe obesity." (PMID 27045805, 2016). "Furthermore, PA in ginger-derived PELNs induces Foxa2 expression in intestinal epithelial cells, thereby preventing high-fat diet-induced obesity and insulin resistance." (PMID 39239509, 2024). "Given the critical role of Foxa2 in regulation of insulin signaling 6, 28-32, this observation motivated us to dissect the role and mechanism of action of this transcription factor in a high-fat diet induced obesity mouse model." (PMID 35154496, 2022). "It has been suggested that the Foxa2 expression level in adipocytes could influence the development and progression of obesity." (PMID 23236435, 2012). "Several of the observed DMCs were located in genes related to T2D or obesity, such as ALOX12, PAMR1, and GNAS in WB; IRS1, LEP, and ADIPOQ in SAT; LCAT, FOXA2, KCNQ1, and GCKR in VAT; and PKD4, HNF4A, XBP1, and PON1 in LT." (PMID 29466957, 2018). "Jejunal EECs isolated from patients with T2DM also demonstrate downregulation in genes involved in EEC differentiation (including PAX4 and FOXA2) and in the GCG gene itself, indicating that jejunal GLP-1+ cell differentiation and number are negatively affected by both obesity and T2DM." (PMID 35503251, 2022).
asthma (13 papers, 2013 to 2025). "We found that the gain and loss of H3K27ac was associated with concurrent changes in asthma-associated gene expression including T2-high signature genes and transcription factors (e.g., FOXA2)." (PMID 33362848, 2020). "Our findings suggest that there are increased IL-6 levels in nocturnal asthma resulting from inhibition of the BMAL1/FOXA2 signalling pathway in airway epithelial cells." (PMID 36505412, 2022). "In contrast, FOXA2 positively regulates MUC5B expression in both idiopathic pulmonary fibrosis and asthma, most likely caused by polymorphism in the MUC5B promoter." (PMID 32269574, 2020). "Significantly, FOXA2 expression is depleted in airways of patients with bronchopulmonary dysplasia, bronchiectasis, and asthma." (PMID 32269574, 2020). "Studies report decreased levels of Foxa2 in allergic diseases and asthma." (PMID 31881038, 2019). "Using DeepSEA, the moderate-to-severe asthma risk allele (G) at the sentinel SNP rs11603634 near MUC5AC was predicted to result in a log2 fold change of more than 1·5 in function at Forkhead Box A1 (FOXA1) and Forkhead Box A2 (FOXA2) binding sites in airway epithelium." (PMID 30552067, 2019). "The association between the asthma risk allele (G) of rs11603634 and increased concentrations of MUC5AC mRNA in bronchial epithelial brush samples, and the predicted effect on FOXA transcription factors provide putative mechanisms because FOXA2 regulates mucin-5AC (MUC5AC) production." (PMID 30552067, 2019). "Therefore, genes associated with defenses may be affected by the depletion of Foxa2 in allergic diseases and asthma." (PMID 31881038, 2019). "IL-13, which is a central mediator of airway remodelling in asthma, increases MUC5AC expression by indirect mechanisms, including STAT6 phosphorylation and suppression of the transcription factor, forkhead box protein A2 (FOXA2)." (PMID 30884895, 2019). "Moreover, reduced expression of airway epithelial FOXA2 and NKX2-1 expression was observed in patients with asthma." (PMID 24282527, 2013). "Given the functional relationship between Foxa2 and Shh, the opposing roles of Shh and Foxa2 in allergic asthma, the role of Hh in driving Th2 differentiation, and the importance of CD4+ Th2 responses in amplifying asthma, we investigated the function of Foxa2 in CD4 T-cells in AAD." (PMID 36003391, 2022). "The OVA-induced asthma model with a circadian rhythm disorder and 16HBE cells treated with serum shock showed an increase in IL-6 levels and a negative correlation with BMAL1 and FOXA2." (PMID 36505412, 2022).
pancreatic cancer (13 papers, 2015 to 2024). "Downregulation of FOXA2 enhanced the metastasis of pancreatic cancer by regulating the epithelial-to-mesenchymal transition (EMT)." (PMID 34551777, 2021). "FOXA2 has a tumor suppressor function through inhibition of pancreatic cancer cell growth, migration, invasion, and colony formation." (PMID 33344262, 2020). "In pancreatic cancer, FOXA2 controls the cis-regulatory networks in a differentiation grade-specific manner." (PMID 33344262, 2020). "The authors showed that FOXA2 knockout using CRISPR/Cas9 vectors in PANC-1 pancreatic cancer cells induced tumor growth in vivo." (PMID 31284594, 2019). "To investigate whether FOXA2 could regulate LINC00261 expression in pancreatic cancer cells, we manipulated FOXA2 levels in PANC-1 cells." (PMID 32414223, 2020). "Furthermore, consistent with the results obtained from miR-1291-expressing pancreatic cancer cells (this study), both FOXA2 and AGR2 protein levels were reduced in cells after transient transfection with miR-1291 expression plasmids (data not shown) or bioengineered miR-1291 agent." (PMID 27322206, 2016). "In summary, Foxa2, as a transcription factor of TOB1, regulates its mRNA expression, while TOB1 participates in the anti‐pancreatic cancer process by regulating the expression of calcium pathway genes." (PMID 31891232, 2020). "IPF1/PDX1 regulates downstream molecules such as Neurogenin 3 (NGN3), Forkhead Box A2 (FOXA2), Hepatocyte Nuclear Factor 1 Beta (HNF1B), Fibroblast Growth Factor Receptor 2 (FGFR2IIIB), and Spondin 1, which are involved in pancreatic development, differentiation, and function in pancreatic cancer." (PMID 39239563, 2024).
type 2 diabetes (13 papers, 2012 to 2025). "Recent genomic studies have shown that FOXA2-bound enhancers in humans are associated with type 2 diabetes (T2D) risk alleles." (PMID 37670346, 2023). "While FOXA2 has been shown to control mRNA levels of PDX1, HNF1A, and HNF4A, mutations in HNF1A, HNF1B, HNF4A, and PDX1 are known to cause maturity-onset diabetes of the young (MODY)." (PMID 39322760, 2024). "In the type 2 diabetes CDC123/CAMK1D GWAS (genome-wide association studies) locus, rs11257655 affects transcriptional activity by altering the binding of the protein complexes of FOXA1 and FOXA2, a potential molecular mechanism in type 2 diabetes." (PMID 35910194, 2022). "We also show differential protein-DNA binding suggesting that the rs11257655 type 2 diabetes- risk allele increased transcriptional activity through binding a protein complex that includes FOXA1 and FOXA2." (PMID 25211022, 2014). "In pancreatic islet cells from type 2 diabetic patients, miR-124a was highly expressed, and its silencing in MIN-6 cells resulted in increased expression of genes involved in insulin secretion, such as Mtpn, Foxa2, Sirt1, and NeuroD1." (PMID 30974824, 2019).
gastric cancer (12 papers, 2015 to 2025). A primary or metastatic malignant neoplasm involving the stomach. "In vitro experiments showed that HDAC3 facilitated the proliferation, migration, and invasion of gastric cancer cells by inhibiting the expression of FOXA2." (PMID 35628623, 2022). "Our analysis, thus, showed that abnormal expression of BMP1, COL1A1, STAT3, GATA6, SOX2 and FOXA2 forms an ubiquitous molecular signature of gastric cancer patients in Southwestern Taiwan." (PMID 29720137, 2018). "MiR‐187 promoted the growth and metastasis of gastric cancer cells by targeting FOXA2 in gastric cancer." (PMID 29464926, 2018). "Among these genes, deregulation of STAT3, GATA6, SOX2, and FOXA2 in gastric cancer was already reported previously in independent studies." (PMID 29720137, 2018). "In gastric cancer, FOXA2-mediated FTO stabilizes MYC mRNA by reducing m6A methylation of MYC." (PMID 37932821, 2023). "In gastric cancer, FOXA2 has been reported to inhibit tumorigenesis both in vitro and in vivo." (PMID 36289750, 2022). "For gastric cancer, the clinical prognosis of patients is related to the expression of FOXA2." (PMID 33166290, 2020). "In gastric cancer, HDAC3 can accelerate the invasion and migration of gastric cancer cells by targeting FOXA2." (PMID 35022030, 2022). "HDAC3-Myc induces FOXA2 transcriptional repression through its regulation on FOXA2-mediated FTO/m6A/MYC axis, leading to the development of gastric cancer." (PMID 34658888, 2021). "Both the human and mouse lncRNA are located downstream of the forkhead box A2 (FOXA2) transcription factor binding site (TFBS) and are suggested to have a role in gastric cancer." (PMID 26496443, 2015).
Hyperinsulinemia (12 papers, 2018 to 2025). An increased concentration of insulin in the blood. "Patients with FOXA2 heterozygous loss-of-function mutation suffered from congenital hyperinsulinism along with endoderm-derived organ malformations." (PMID 39532884, 2024). "We expand the known phenotype on FOXA2 mutations and report a likely pathogenic, novel mutation associated with hyperinsulinism and panhypopituitarism." (PMID 37219505, 2023). "Our study reports a likely pathogenic novel mutation in the FOXA2 gene in a patient presenting with hyperinsulinism and panhypopituitarism." (PMID 37219505, 2023). "Additional research has revealed that SCHAD deficiency also plays an important role in hyperinsulinemia induced by knockout of the islet specific transcription factor Fork head box A2 (FOXA2) gene." (PMID 34736508, 2021). "Recently, de novo heterozygous FOXA2 mutations have been reported in patients with the clinical phenotype of congenital hypopituitarism, hyperinsulinism, hypoglycemia, and endometrial‐derived organ abnormalities." (PMID 32277595, 2020). "Recently, two studies reported an association of FOXA2 heterozygous mutations with hyperinsulinism, hypoglycemia, pituitary hormone deficiency, craniofacial, and endoderm‐derived organ abnormalities." (PMID 32277595, 2020). "Patients with heterozygous FOXA2 mutations appear to exhibit hyperinsulinemia and hypoglycemia." (PMID 32277595, 2020). "FOXA2 mutation may lead to the rare combination of hyperinsulinism and panhypopituitarism." (PMID 37219505, 2023). "For example, in the fasting (low insulin) state, FOXA2 activates transcriptional programs of lipid metabolism and ketogenesis, whereas, in hyperinsulinemia, FOXA2 is inactivated, thereby promoting hepatic lipid accumulation and insulin resistance." (PMID 38605023, 2024). "For example, Foxa2 is permanently inactive and located in the cytoplasm of hepatocytes in hyperinsulinemia/obese mice, which favors the development of hepatic steatosis and insulin resistance." (PMID 38084145, 2023). "Consistent with genetic screening results in patients with congenital hyperinsulinemia, FOXA2 inactivation in mature Β cells induced hyperinsulinemia and hypoglycemia." (PMID 36798663, 2023). "Chronic hyperinsulinemia in insulin-resistant syndrome results in the cytoplasmic localization and inactivation of Foxa2 6, 7, thereby promoting lipid accumulation and insulin resistance in the liver." (PMID 35154496, 2022). "It is known that chronic hyperinsulinemia in insulin-resistant syndromes results in the cytoplasmic localization and inactivation of FoxA2, thereby promoting lipid accumulation and insulin resistance in the liver." (PMID 30024933, 2018). "FOXA2 point mutations and deletions have also been reported patients with syndromic hypopituitarism but without documented hyperinsulinism (reviewed by 124)." (PMID 37065762, 2023). "Therefore, it could be hypothesized that fetal hyperinsulinemia leads to FOXA2 phosphorylation, and then, p‐FOXA2 is discharged from the nucleus." (PMID 30338211, 2018).
Insulin resistance (12 papers, 2016 to 2025). Increased resistance towards insulin, that is, diminished effectiveness of insulin in reducing blood glucose levels. "Furthermore, a high-fat diet, an important causative factor of insulin resistance, downregulated GnT-IVa expression in the pancreas due to abnormal export of the key transcription factors forkhead box protein A2 (FOXA2) and hepatocyte nuclear factor 1-alpha (HNF1A) from the nuclei." (PMID 27136596, 2016). "Other authors suggested that ginger-derived nano particles can prevent insulin resistance in high-fat diet fed mice by increasing the expression of Foxa2 and protecting Foxa2 from AKT-1 mediated phosphorylation, ensuring inactivation of Foxa2." (PMID 38671840, 2024). "The importance of this AKT/FOXA2/PDX1 axis in adaptation of β-cells to insulin resistance is only observed in conditions of reduced mTORC1 activity." (PMID 37423392, 2023). "Here, we report that treatment with orally administered ginger-derived nanoparticles (GDNP) prevents insulin resistance by restoring homeostasis in gut epithelial Foxa2 mediated signaling in mice fed a high-fat diet (HFD)." (PMID 35154496, 2022). "In insulin-resistant mice, Foxa2 is inactive and permanently located in the cytoplasm of hepatocytes." (PMID 35154496, 2022). "Because of this, the link between GDNP mediating an increased expression of intestinal epithelial cell Foxa2 and insulin resistance was further investigated." (PMID 35154496, 2022). "However, insulin resistance impairs fatty acid oxidation, a process regulated by forkhead box protein A2 (FOXA2)." (PMID 40893881, 2025). "In addition, the oral supplementation of ginger-derived exosomal nanoparticles prevented insulin resistance in obese mice by increasing the expression of Foxa2." (PMID 40649784, 2025). "In addition to anti-inflammatory effects, PA from GG-DVs induces Foxa2 expression and prevents Foxa2 phosphorylation to prevent high-fat diet-induced insulin resistance." (PMID 40826362, 2025). "Besides, GDNP prevents insulin resistance by blocking Akt-1-mediated Foxa2 phosphorylation and restoring homeostasis of intestinal epithelial and hepatic Foxa2 signaling in HFD-fed mice." (PMID 38195552, 2024). "Foxa2 has been identified as an insulin-sensitive transcriptional regulator that modulates gene expression involved in glucose and lipid metabolism pathways and improves insulin resistance in peripheral tissues." (PMID 38084145, 2023). "Specifically, in this study, using our understanding of intestine/liver crosstalk, we address whether new therapeutic strategies for prevention of high-fat diet induced insulin resistance via targeting Foxa2 are possible." (PMID 35154496, 2022). "Increasing expression of Foxa2 leads to altering the composition of intestinal epithelial cell (IEC) exosomes of mice fed a HFD and prevents IEC exosome mediated insulin resistance." (PMID 35154496, 2022). "The role of intestinal epithelial Foxa2 in high-fat diet induced insulin resistance has not been studied." (PMID 35154496, 2022). "Finally, these studies also reveal that increasing FOXA2 levels in islets with reduced mTORC1 activity rescue PDX1 levels and insulin secretion, highlighting the importance of the AKT/FOXA2/PDX1 axis as a possible therapeutic tool to improve β-cells in conditions of insulin resistance." (PMID 37423392, 2023).
lung adenocarcinoma (12 papers, 2015 to 2025). A carcinoma that arises from the lung and is characterized by the presence of malignant glandular epithelial cells. "Other important proteins in this group were the transcription factors FOXA1 and FOXA2 that have been reported as the initiating factors of a cellular transdifferentiation program that generates gastric-like tissue in lung adenocarcinomas." (PMID 39296813, 2021). "In lung adenocarcinoma, the developmental transcription factors FOXA2 and Cdx2 function cooperatively with Nkx2-1 as an important regulator in inhibiting metastasis." (PMID 31007610, 2019). "Here, we show that the transcription factors FoxA1 and FoxA2 are required for initiation of mucinous NKX2-1-negative lung adenocarcinomas in the mouse and for activation of their gastric differentiation program." (PMID 30475207, 2018). "Recent study identified Bax as a putative target gene of FOXA2 in lung adenocarcinoma cells by screening techniques." (PMID 29456509, 2018). "FoxA1 and FoxA2 are required for initiation and proliferation of NKX2-1-deficient lung adenocarcinoma." (PMID 30475207, 2018). "In NCI-H358 human lung adenocarcinoma cells, Halmos’ group reported that overexpression of FOXA2 reduced growth, arrested proliferation, and increased apoptosis." (PMID 29456509, 2018). "To address this question directly, we used conditional alleles of Foxa1 and Foxa2 to abrogate their function in an autochthonous mouse model of NKX2-1-negative lung adenocarcinoma." (PMID 30475207, 2018). "Here, we show that FoxA1 and FoxA2 are required for lung adenocarcinomas to adopt a mucinous, gastric differentiation state in the absence of NKX2-1." (PMID 30475207, 2018). "Furthermore, the inferred activity of FOXA2, FOXM1, and UHRF1 were significantly associated with survival in several lung adenocarcinoma cohorts." (PMID 31503425, 2019). "To test the hypothesis that FoxA1/2 are required for lung adenocarcinoma cells to undergo a pulmonary to gastric lineage switch upon loss of NKX2-1 expression, we incorporated conditional alleles of Foxa1 and Foxa2 into a mouse model of NKX2-1-deficient lung adenocarcinoma." (PMID 30475207, 2018). "We show that FoxA1 and FoxA2 regulate the growth and gastric identity of NKX2-1-negative lung adenocarcinoma." (PMID 30475207, 2018). "Moreover, after being induced by forkhead box protein A2 (FOXA2), the overexpression of LINC00261 in lung adenocarcinoma (LUAD) cells slowed cell proliferation by inducing G2/M cell-cycle arrest." (PMID 34022894, 2021). "Additionally, FOXA2 and CDX2 cooperate with NKX2-1 to inhibit metastasis in lung adenocarcinoma." (PMID 36289750, 2022).